EGFR (epidermal growth factor receptor)
Diseases named in the same sentence as EGFR in open-access papers (continued):
Sharing a sentence is not in itself a finding about the gene and the disease.
lung adenocarcinoma (continued). "In our study, 80% (16/20) of lung adenocarcinomas with MLCs harbored an EGFR mutation, higher than those adenocarcinomas without MLCs, which was similar to previous research." (PMID 34234879, 2021). "EGFR L718Q has been reported as one of the rare resistance mechanisms to osimertinib therapy in an EGFR L858R/T790M-positive lung adenocarcinoma patient, which might be sensitive to afatinib." (PMID 34660287, 2021). "A 45-year old man with 60 pack-year smoking history (P05) was diagnosed with EGFR L858R-mutant stage IV lung adenocarcinoma and received a combination of osimertinib and crizotinib after acquiring MET amplification with an absolute CN of 4.98 at disease progression from first-line erlotinib therapy." (PMID 34660287, 2021). "Therefore, it is of interest to explore the interaction between caspase-8 and c-Src and their effect on the clinical efficacy of TKIs in EGFR-mutant lung adenocarcinoma." (PMID 34367939, 2021). "In addition, one study has reported that microRNAs, metabolic pathways, and pseudohypoxia initiate drug tolerance to EGFR inhibitors in lung adenocarcinoma." (PMID 34381712, 2021). "Nevertheless, our in vitro and in vivo findings fully support the notion that EGFR/MEK combination might be a viable option to overcome BRAF-driven resistance in patients with EGFR-mutant lung adenocarcinoma." (PMID 34921211, 2021). "The correlation between BMP5 and EGFR expression and mutations suggests that BMP5 may affect EGFR-targeted therapy in lung adenocarcinoma." (PMID 34745928, 2021). "No specific recommendations for patients with EGFR-mutated lung adenocarcinoma were found in these guidelines." (PMID 34201833, 2021). "We performed immunohistochemistry analyses of resected lung adenocarcinoma tissues with and without EGFR mutations to investigate and compare the characteristics of the tumor microenvironment (TME)." (PMID 34484468, 2021). "Additionally, different from lung adenocarcinoma (LUAD), which has greatly benefited from targeted therapies against driver mutations such as epidermal growth factor receptor (EGFR) mutations, etc., inroads in targeted therapy are rare in SqCLC." (PMID 34992605, 2021). "Epidermal growth factor receptor (EGFR) mutations are a common molecular therapeutic target occurring in approximately 40%–60% of Asian patients and 10%–20% of Caucasian patients with lung adenocarcinomas." (PMID 33626238, 2021). "Like other activating mutations in the EGFR gene, their frequency is higher among women, Asian patients, patients diagnosed with lung adenocarcinoma and non-smoking patients; they are also mutually exclusive with other molecular alterations." (PMID 33921237, 2021). "Patients with lung adenocarcinoma with CNS metastases, without activating EGFR mutation and without ALK rearrangement, benefit from immunotherapy." (PMID 33435596, 2021). "Pre-clinical studies have shown that efatutazone in combination with chemotherapy can increase cancer cell death, inhibit proliferation, and suppress cancer cell motility of particularly epidermal growth factor receptor-tyrosine kinase inhibitor (Egfr-Tki)-resistant lung adenocarcinoma cells." (PMID 34195082, 2021). "We previously found that TSHZ2 had a negative correlation with EGFR mutations, with EGFR wild-type patients with lung adenocarcinoma showing an expression rate of 32.4%." (PMID 33850468, 2021). "In addition to EGFR, ALK-EML4 fusion, KRAS mutation, HER2 amplification, and PIK3CA mutation were also found in lung adenocarcinomas with MLCs." (PMID 34234879, 2021). "After being compared with the results of the EGFR-mutant lung adenocarcinoma patients treated by gefitinib alone, dual drugs of gefitinib and dasatinib achieved the better response rate and duration as compared with gefitinib alone, which led to a better prognosis for OS." (PMID 34367939, 2021).
lung adenocarcinoma (continued). "The present study examined the relationship between the WWOX single-nucleotide polymorphisms (SNPs; rs11545028, rs12918952, rs3764340, rs73569323, and rs383362) and the clinicopathological factors in lung adenocarcinoma patients with or without EGFR mutations." (PMID 34948746, 2021). "By identifying the bottom 50% PD-L1 expression level as PD-L1 low expression and removing EGFR mutant samples, a total of 640 lung adenocarcinoma (LUAD) and lung squamous carcinoma (LUSC) tumor samples and 93 adjacent non-tumor samples were finally extracted from The Cancer Genome Atlas (TCGA)." (PMID 34595103, 2021). "H3K27ac ChIP-seq analyses of 69 FFPE samples using a dual-arm robot revealed that driver mutations in EGFR were distinguishable from pan-negative cases and were relatively homogeneous as a group in lung adenocarcinomas." (PMID 33924956, 2021). "In order to evaluate the presence and the proportion of CSCs, ALDH enzymatic activity was assessed using the ALDEFLUOR assay in three lung adenocarcinoma cell lines with different KRAS and EGFR mutational status: two KRAS mutant cell lines (A549 and H1734) and one EGFR mutant cell line H1975." (PMID 34127680, 2021). "Furthermore, a reverse correlation was observed between FBXL2 and EGFR protein expression in TMA of lung adenocarcinoma and lung squamous cell carcinoma." (PMID 34635651, 2021). "Given that c-Src activation is frequent in lung adenocarcinoma, blocking c-Src activation through dasatinib can seal the survival-signaling-related phosphotyrosines of EGFR by its SH2 domain, which in turn increases the antitumor activity of TKIs in EGFR-mutant lung adenocarcinoma." (PMID 34367939, 2021). "A non-smoking 53-year-old male patient with lung adenocarcinoma underwent gefitinib, afatinib, and osimertinib combined with crizotinib treatment and developed different EGFR resistance mutations." (PMID 34397683, 2021). "Several clinical trials have shown improved efficacy, better outcomes in progression-free survival (PFS) and/or overall survival (OS) for several generations of TKI as compared to patients with EGFR-mutant lung adenocarcinoma who received chemotherapy as adjuvant treatment." (PMID 34439273, 2021). "By identifying the bottom 25% PD‐L1 expression level as low expression of PD‐L1 and removing EGFR mutant samples, a total of 222 lung adenocarcinoma (LUAD) and lung squamous carcinoma (LUSC) samples and 93 adjacent non‐tumor samples were finally extracted from The Cancer Genome Atlas (TCGA)." (PMID 34250747, 2021). "Therefore, EGFR is a widely accepted therapeutic target, either using small molecule tyrosine kinase inhibitors (e.g., erlotinib in lung adenocarcinoma) or blocking antibody (e.g., cetuximab in HNSCC)." (PMID 34725466, 2021). "The patients enrolled in this study were mainly lung adenocarcinoma, females, non-smokers, and EGFR mutation carriers." (PMID 33531991, 2021). "Based on these results, EGFR-mutated stage II lung adenocarcinoma should not be treated with conventional surgery plus adjuvant chemotherapy, but the adjuvant or neoadjuvant treatment should include TKIs." (PMID 34298845, 2021). "Patient CL0196 had small cell carcinoma that transformed from an Epidermal Growth Factor Receptor (EGFR) mutant lung adenocarcinoma following anti-EGFR therapy and had a confirmed partial response (PR) after 8 weeks on treatment with an ongoing response at data cutoff." (PMID 34162872, 2021). "The first-generation EGFR TKIs, gefitinib and erlotinib, designed to reversibly compete for the adenosine triphosphate binding sites and, thus, block EGFR-induced downstream signaling activation in the lung adenocarcinoma treatment." (PMID 34367939, 2021).
lung adenocarcinoma (continued). "Surprisingly, we found that systemic administration of DT induced rapid regression of murine lung adenocarcinomas that express human mutant EGFR in the absence of a transgenic allele containing human DTR." (PMID 34494649, 2021). "In summary, our study is the first to clarify the detailed differences in immunological landscape in lung adenocarcinoma with and without EGFR mutation." (PMID 34484468, 2021). "Two lung adenocarcinoma patients with EGFR mutations who recurred after radical resection transformed into SCLC under treatment with the sequential first- and third-generation EGFR-TKIs." (PMID 33725888, 2021). "Additionally, the CD133+ population was sensitive to the EGFR-TKI afatinib in EGFRm lung adenocarcinoma H1650 and H1975 cell lines." (PMID 34771484, 2021). "Hence, we examined if CDK9 inhibitors can eliminate lung adenocarcinoma cells that are resistant to the third-generation EGFR inhibitor, Osimertinib, or the recently developed K-Ras G12C inhibitor, AMG510 (Sotorasib)." (PMID 34359807, 2021). "Cancer immunotherapy is ineffective in low TMB EGFR-mutant lung adenocarcinoma." (PMID 34391887, 2021). "Furthermore, while the deep learning model was trained using scanned frozen tissue slides, a reasonable level of generalisability was observed when applying the model to predict EGFR status in FFPE lung adenocarcinoma slides." (PMID 34441338, 2021). "Recent studies by Wang et al31 found that GGO volume percentages were significantly higher in patients with primary lung adenocarcinomas and EGFR mutation than in adenocarcinomas without EGFR mutation." (PMID 33314737, 2021). "Targeted sequencing revealed that lung adenocarcinoma harbored EGFR mutations, whereas no mutations were detected in either component of biphasic mesothelioma." (PMID 34333253, 2021). "Our data also indicated that RhoV induced progression and EGFR-TKI resistance of lung adenocarcinoma may be related to the activation of the AKT/ERK pathway." (PMID 33767988, 2021). "Therefore, we hoped to uncover the relationship between c-Src activation and EGFR signaling in lung adenocarcinoma." (PMID 34367939, 2021). "EGFR signaling is one important driving mechanism in lung adenocarcinoma, and we further examined whether EGFR regulates the activation of DRP1." (PMID 33152171, 2021). "Osimertinb and atezolizumab had stronger cytotoxic synergism compared to osimertinib and nivolumab in both osimertinib-sensitive, EGFR-mutant (11 ± 6% vs 25 ± 6%, P < 0.05) and osimertinib-resistant, EGFR-mutant lung adenocarcinomas (8 ± 1% vs 28 ± 3%, P < 0.05)." (PMID 34488906, 2021). "This sheds light on the lack of research on the underlying mechanism of EGFR TKIs, which must be investigated to enhance the therapeutic potency in lung adenocarcinoma." (PMID 34367939, 2021). "Of the patients with EGFR-mutated lung adenocarcinoma, 52.3% had no mutations in addition to the EGFR mutation, 33.9% had one concomitant mutation, and 10% had more than two concomitant mutations." (PMID 34298845, 2021). "Based on this study, Sema7A levels may be considered a biomarker of mTOR pathway activation, useful for guiding therapeutic decisions in EGFR-dependent lung adenocarcinoma patients." (PMID 33537086, 2021). "Based on the database of drug targets in 324 human cancer cell lines from 30 cancer types, we found that EGFR is an anti-cancer target in Squamous Cell Lung Carcinoma, Lung Adenocarcinoma, Oral Cavity Carcinoma, Ovarian Carcinoma, Head and Neck Carcinoma and Esophagus." (PMID 33968733, 2021). "The relationship between ER and EGFR has also been widely studied in lung adenocarcinoma." (PMID 34548052, 2021). "In this study, 52.5% (1,443/2,751) of the cases tested by NGS did not carry EGFR mutations, similar to the results reported in previous Asian lung adenocarcinoma series." (PMID 34257561, 2021). "Moreover, the deletion of the SH2 domain of c-Src completely eliminated its interaction with EGFR in the EGFR-mutant lung adenocarcinoma." (PMID 34367939, 2021).
lung adenocarcinoma (continued). "For stage IV lung adenocarcinoma patients harboring EGFR mutations, tyrosine kinase inhibitor (TKI) is recommended to be the first-line treatment modality especially for Asian patients with a relatively higher possibility of EGFR mutations." (PMID 34354943, 2021). "Furthermore, our team retrospectively analyzed all the patients with EGFR-mutant lung adenocarcinoma in our center." (PMID 34367939, 2021). "Epidermal growth factor receptor (EGFR) is a key oncogene in lung adenocarcinoma (LUAD)." (PMID 33568630, 2021). "In conclusion, these data indicate that WWOX SNPs may help predict tumor growth and invasion in patients with EGFR mutant lung adenocarcinoma, especially those with the EGFR-L858R mutant in Taiwan." (PMID 34948746, 2021). "In this study, EGFR mutations were identified in 56% of patients with early stage NSCLC, which is higher than that in previous reports (30–40% in patients with early stage lung adenocarcinoma in Asia)." (PMID 34109114, 2021). "Second, EGFR mutation and ALK gene fusion are mutually exclusive events in lung adenocarcinoma." (PMID 34559836, 2021). "Based on the analysis of RNA-sequencing data, we identified a fusion transcript of CD63–BCAR4 in a Korean patient with lung adenocarcinoma who did not harbour any known activating mutations in EGFR and KRAS genes." (PMID 33204025, 2021). "We evaluated the anti-tumor properties of afatinib and osimertinib in four EGFR-mutant lung adenocarcinoma cell lines (i.e., PC-9, HCC827, H1975, and H1650) by the 3-(4,5-dimethylthiazol-2-yl)-5-(3-carboxymethoxyphenyl)-2-(4-sulfophenyl)-2H-tetrazolium, inner salt (MTS) assay." (PMID 33924522, 2021). "The proposed deep learning-based model could help clinicians identify suitable advanced patients with lung adenocarcinoma for EGFR-targeted therapy, facilitating implementation of precise medicine with an efficient and convenient way." (PMID 34367993, 2021). "EGFR mutation was more common in the lung adenocarcinomas accompanied with MLCs than lung adenocarcinomas without MLCs (χ2 = 4.339, P = 0.040)." (PMID 34234879, 2021). "Comparing to low UGT2B7 expression, patients with high UGT2B7 expression had significant poor overall survival among never‐smoking female Asian lung adenocarcinoma patients with EGFR mutation (HR = 4.80, 95% CI = 1.18–14.21, p = 0.027)." (PMID 33595913, 2021). "Different copy number profiles in lung adenocarcinoma tumors with and without mutations in EGFR or KRAS have been described, but information about structural events have not been included in these studies." (PMID 34625038, 2021). "Furthermore, combination treatment with AKIs and EGFR inhibitors was found to robustly decrease tumor growth in an EGFR-mutant lung adenocarcinoma PDX model." (PMID 34956905, 2021). "Our data suggest that WWOX SNPs may help to predict tumor growth and invasion in patients with EGFR mutant lung adenocarcinoma, especially those with the EGFR-L858R mutant." (PMID 34948746, 2021). "Therefore, we performed this multi-center retrospective study in R0-resected EGFR-mutant pathologic N2 lung adenocarcinoma to evaluate the optimal adjuvant systemic treatments and other prognostic factors of clinical outcomes." (PMID 33916930, 2021). "Based on extended research in lung adenocarcinoma, it is current knowledge that almost all EGFRex20ins confer in vitro and clinical resistance to first- and second-generation EGFR tyrosine kinase inhibitors (TKIs), although osimertinib had shown clinical efficacy against some of these mutations." (PMID 34885191, 2021). "Notably, the oncogenic driver mutations, such as EGFR and KRAS, are commonly observed in lung adenocarcinoma." (PMID 34884633, 2021).
lung adenocarcinoma (continued). "The most common molecular markers for lung adenocarcinoma are epidermal growth factor receptor (EGFR) and Kirsten ras (KRAS), both of which may occur in nearly 30% of all cases (Testa, Castelli & Pelosi, 2018)." (PMID 33604163, 2021). "We report a case of impressive radiological and ctDNA response under dabrafenib, trametinib, and osimertinib in an advanced EGFR-mutant lung adenocarcinoma patient who developed BRAF V600E as one of the acquired resistance mechanisms to second-line osimertinib." (PMID 33580193, 2021). "Increased EGFR expression was observed in the pleural microvessels of patients with lung adenocarcinoma both with and without mutations in EGFR." (PMID 34680445, 2021). "Having established this novel RCRA ChIP-seq procedure, we performed H3K27ac ChIP-seq for 69 lung adenocarcinomas (LUADs) using a dual-arm robot, revealing that driver mutations in EGFR were epigenetically distinguishable from pan-negative cases." (PMID 33924956, 2021). "We previously reported that the mTOR pathway not only serves as a predictive marker for sensitivity to the combination of the EGFR‐TKI inhibitor WZ4002 and trametinib, but also is involved in acquired resistance to this combination treatment in EGFR mutant lung adenocarcinoma." (PMID 32191822, 2021). "Moreover, GGA2 reportedly maintains the cell surface expression of EGFR necessary for robust cell growth, and is recognized as a cooperative driver of EGFR-mediated lung adenocarcinoma, suggesting a new role of GGA2 in supporting cancer cell growth." (PMID 34799560, 2021). "We retrospectively enrolled 232 patients with EGFR-mutant lung adenocarcinoma with BMs." (PMID 34847914, 2021). "Therefore, the purpose of our study was to investigate the differences in CT characteristics and disease spread patterns between patients with lung adenocarcinoma who have ROS1 rearrangement and those with EGFR mutations or ALK rearrangement." (PMID 33005033, 2020). "In addition, the coexistence of positive MET FISH status and EGFR mutations is associated with shorter DFS and OS after surgery in patients with lung adenocarcinoma." (PMID 33363040, 2020). "FFPE tumor tissue blocks from 36 surgical specimens of lung adenocarcinomas with known EGFR mutation statuses were obtained without patient identifiers from St." (PMID 32983988, 2020). "The EML4-ALK rearrangement gene has high prevalence in selected lung adenocarcinoma and EGFR mutation-negative populations." (PMID 33425389, 2020). "To determine whether knockdown of Mig-6 and treatment with an EGFR-TKI has a synergistic effect in killing EGFR-TKI-resistant lung adenocarcinoma, we knocked down Mig-6 using shRNA and evaluated the effect on cell proliferation and EGFR-TKI sensitivity." (PMID 32552717, 2020). "Lower than expected variant allele frequency of IDH1/2 mutants and coexistence of IDH1/2 mutations with known trunk drivers in the BRAF, EGFR, and KRAS genes suggest they could be branching drivers leading to subclonal evolution in lung adenocarcinomas." (PMID 32333643, 2020). "The EGFR impact score is a novel prognostic and therapeutic indicator for lung adenocarcinoma." (PMID 32277151, 2020). "In the United States, the frequency of EGFR testing was reported to be only 22% for Stage IV lung adenocarcinoma in the whole country in 2010, though the guidelines recommend systematic testing for all Stage IV lung adenocarcinomas." (PMID 33272243, 2020).